APOE (apolipoprotein E)
Diseases named in the same sentence as APOE in open-access papers (continued):
Sharing a sentence is not in itself a finding about the gene and the disease.
atherosclerosis (continued). "By employing LysM-Cre-driven expression of human ORP2 in macrophages and combining this with ApoE−/− atherosclerosis-prone mice, we reveal that ORP2 enhances the nuclear translocation of LXRα in macrophages, promoting cholesterol efflux and reducing foam cell formation." (PMID 40349776, 2025). "For this purpose, the potential effects of propolis extracts on inflammatory and oxidative stress biomarkers (OxLDL and LOX-1) in atherosclerosis, as well as atherosclerotic plaque development in ApoE−/− mice fed a HFD, were investigated using both biochemical and histological methods." (PMID 40283120, 2025). "APOE reduces inflammation by neutralizing LPS and regulating NF-κB signaling in macrophages, thereby limiting inflammatory cytokine production and atherosclerosis." (PMID 40612951, 2025). "The administration of DMB via the drinking water resulted in lower foam cell formation from macrophages and reduced atherosclerotic plaque sizes in ApoE−/−mice, suggesting that targeting of microbial enzymes could reduce atherosclerosis burden." (PMID 40741383, 2025). "Furthermore, we established an HFD-fed ApoE-KO mouse model that developed atherosclerosis combined with hypercholesterolemia." (PMID 41194853, 2025). "The recent studies showing that targeted delivery of the MerTK protein in macrophages improves efferocytosis and reduces atherosclerosis in diabetic ApoE−/− mice and the aPC mediated restoration of MerTK in the current study supports the translational relevance of the current study." (PMID 41083981, 2025). "IGFBP5 promotes atherosclerosis in ApoE−/− mice through the phenotypic transformation of VSMCs." (PMID 40729024, 2025). "Additionally, shikonin (SKN), a natural naphthoquinone, has been shown to attenuate HHcy-induced atherosclerosis in ApoE−/− mice by inhibiting metabolic reprogramming in CD4+ T cells." (PMID 39898976, 2025). "Additionally, mtDNA damage worsens atherosclerosis in ApoE KO mice with impaired mtDNA polymerase proofreading activity, which correlates with signs of plaque vulnerability." (PMID 40700116, 2025). "We next fed ApoE–/– mice with a high‐fat diet for 8 weeks to induce atherosclerosis." (PMID 40391195, 2025). "In apolipoprotein E‐deficient (APOE−/−) AS mice, Arg2 impairs endothelial autophagy by regulating mTOR and protein kinase AMP‐activated protein kinase (AMPK) and AMPK signalling pathways in advanced atherosclerosis." (PMID 40497340, 2025). "In addition to its interactions with MMP9 and ADORA2A, ACE2 also showed connections with Apolipoprotein E (APOE), a protein that plays a central role in lipid metabolism and atherosclerosis." (PMID 40142959, 2025). "A model of atherosclerosis was established in ApoE−/− mice fed HFD." (PMID 40283120, 2025). "Using various mouse models, including Bmal1−/− (brain and muscle Arnt-like protein 1) and ApoE−/− mice, the study demonstrated that P. gingivalis infection accelerated atherosclerosis progression by triggering oxidative stress and inflammatory responses in the arteries." (PMID 40001895, 2025). "This study extends these findings to an atherosclerosis model with a more human-like lipoprotein profile, where apoE is still present, and demonstrating reduction at the protein level, both at the (diseased) endothelial lining of lung and aortic root and the circulating plasma pool." (PMID 40093962, 2025). "Similarly, previous findings showed that, in atherosclerosis-prone mice devoid of ApoE, treatment with antagonists of RAGE or its genetic deletion reduced atherosclerotic lesion area and macrophage content." (PMID 39999114, 2025).
atherosclerosis (continued). "Pulp and peel extract were given to high-fat diet-fed ApoE−/− mice by gavage to determine whether FC extracts could play a beneficial role in atherosclerosis." (PMID 41515139, 2025). "Consistently, Febuxostat at 2.5 mg/kg/day for 12 weeks significantly inhibited plasma XO activity, reduced atherosclerotic plaque formation, and decreased macrophage infiltration in the aortic root, indicating protection against atherosclerosis in ApoE−/− mice fed a high-cholesterol diet." (PMID 41382274, 2025). "ApoE/caspase-1 double knockout models demonstrate a slower progression of atherosclerosis." (PMID 39936975, 2025). "The hAPOE*2/*2 mice are well-established transgenic mice known for their susceptibility to atherosclerosis while maintaining cholesterol distribution across all 3 major lipoprotein compartments, unlike other atherogenic backgrounds like ApoE-KO." (PMID 40591411, 2025). "Although, a 2013 study that increased CTLA-4 activity using abatacept in APOE 3-leiden mice found a reduction in the severity of atherosclerosis through a dramatic 78.1% decrease in arterial thickening, thus offering a different avenue for ICI therapy in atherosclerosis treatment." (PMID 40552286, 2025). "Blockade of APOA1 cleavage by AEP diminishes atherosclerosis in APOE–/– mice." (PMID 40371638, 2025). "Eventually, in ApoE-deficient mice, BRL 37344 decreases aortic atherosclerotic lesion areas and attenuates fibrous cap formation, suppressing lesion progression, thus alleviating atherosclerosis." (PMID 41465273, 2025). "In addition, circulating P/E selectin and CD31 concentrations were diminished in serum of ApoE−/−AnxA8−/− compared with ApoE−/− AnxA8+/+ mice in either the early or the advanced model of atherosclerosis." (PMID 39835780, 2025). "ApoE−/− mice are known to exhibit delayed lipoprotein clearance, which contributes to the development of hyperlipidemia or dyslipidemia and ultimately leads to atherosclerosis, resembling human pathological conditions." (PMID 40867851, 2025). "Therefore, we will continue to use ApoE−/− mice to build a hyperlipidemia-induced arterial atherosclerosis model to verify the role of CDCP1 in lipid metabolism." (PMID 40256729, 2025). "Animal studies also confirmed that DEHP exposure can lead to hyperlipidemia and atherosclerosis development in ApoE-/- mice, which featured increased levels of inflammatory cytokines (e.g., Tnf-α, Mcp-1) in aorta, and elevated expression of key atherogenic genes (e.g., Icam-1, Vcam-1) in ECs." (PMID 40857741, 2025). "In this study, we used the ApoE−/− mice as a model of atherosclerosis." (PMID 40718724, 2025). "Mice with ApoE−/−P-Jak2 deficiency developed accelerated atherosclerosis in both sexes, while not displaying significant metabolic abnormalities or differences in plaque characteristics." (PMID 40825505, 2025). "Additionally, the protective effects of GLSP on the aged vasculature were assessed by examining atherosclerosis in apoE-/- mice and vascular calcification in VD3 and nicotine-induced mice." (PMID 40225574, 2025). "Six‐week‐old male ApoE−/− mice were fed a high‐fat diet for 12 weeks to induce atherosclerosis." (PMID 41244340, 2025). "BMT demonstrate that deletion of LXN in bone marrow protects ApoE-/- mice against atherosclerosis." (PMID 39424784, 2024). "ApoE−/− mice completely lack the APOE gene, whereas E3L mice express a variant of APOE; these differences result in distinct lipid metabolism and inflammatory responses, which are critical factors in atherosclerosis." (PMID 39449970, 2024).
atherosclerosis (continued). "However, it should be noted that this model mimics features of early atherosclerosis and that further research using other models (eg, ApoE−/−) is required to fully appreciate the role of Epas1 in disease progression." (PMID 39234692, 2024). "Furthermore, feeding ApoE-/- mice with a high-fat diet additionally increases plasma CH levels and accelerates atherosclerosis development." (PMID 38474500, 2024). "This study provides novel evidence of the vascular protective effects of Met on atherosclerosis and some of its underlying mechanisms in nondiabetic ApoE KO mice." (PMID 39223261, 2024). "Furthermore, we took advantage of the atherosclerosis-prone ApoE-/- mouse model to investigate the role of CD40 signaling on atherosclerosis (ATS) progression." (PMID 39767610, 2024). "Similarly, a recent study presented increased blood neutrophil numbers and their activation responses in ApoE−/− mouse model of atherosclerosis." (PMID 39845972, 2024). "The ApoE−/− mice is currently a widely used model for studying atherosclerosis." (PMID 39629078, 2024). "In this study, we investigate the effect of 17-beta estradiol on the beta cell UPR using a mouse model of hyperglycemia-induced atherosclerosis, the ApoE−/−:Ins2+/Akita mouse, which exhibits sexual dimorphism in terms of glucose regulation and atherosclerosis progression." (PMID 38339098, 2024). "However, apoE KO mice expressing only apoB48 also had higher TC levels in plasma thus complicating the role of apoB48 in the development of atherosclerosis." (PMID 39087075, 2024). "ApoE−/− mice reconstituted with CD27-deficient bone marrow show significantly larger plaque sizes and a decreased abundance of Tregs compared to mice receiving CD27+/+ApoE−/− bone marrow, particularly in the early stages of atherosclerosis." (PMID 39926714, 2024). "The result of a study demonstrated that lentivirus-mediated NFIA overexpression resulted in increased circulation of HDL-C, reduced levels of LDL-C, and very low density lipoprotein (VLDL-C), contributing to atherosclerosis regression in apolipoprotein E (apoE) knockout mice." (PMID 39273193, 2024). "Injection of these cells into the tail vein of male C57BL/6 apolipoprotein E knockout (apoE-KO) mice fed with a high-fat diet alleviated the progression of atherosclerosis by reducing macrophage accumulation and suppressing the inflammatory response in the aortic arteries." (PMID 38612710, 2024). "Levels of circUBAC2 were lower in the mice with atherosclerosis (ApoE−/−) than in the WT mice." (PMID 39201700, 2024). "In addition, we adopted ApoE−/− mice for in vivo validation, which is currently the most widely used preclinical model of atherosclerosis." (PMID 39495676, 2024). "ApoE−/− mice fed a high fat diet (HFD) were used to establish an atherosclerosis model." (PMID 39449970, 2024). "Murine studies of APOE−/− mice on a high-fat diet infected with viruses such as HHV8 (MHV-68) had accelerated atherosclerosis, which further supports a possible role for HHV8 in accelerating atherosclerosis in the presence of other CVD risk factors." (PMID 38781301, 2024). "Additionally, research has demonstrated that the progression of atherosclerosis in ApoE−/− mice closely resembles type II hyperlipidemia in humans." (PMID 39629078, 2024). "These micelles were used as an atherosclerosis model on apolipoprotein E−/− (ApoE−/−) mice." (PMID 38794614, 2024).
atherosclerosis (continued). "The anti‐inflammatory property of apolipoprotein E (apoE) could protect against atherosclerosis by regulating cellular microRNA levels in leukocytes." (PMID 39392102, 2024). "Thus, to test the EC-autonomous role of ATGL during atherosclerosis, congenic Atgl ECKO mice were bred to Apoe-deficient mice (ApoE–/–) and fed an atherogenic diet (40% Kcal from fat plus 1.25% cholesterol) for 12 weeks." (PMID 38175710, 2024). "The inhibition of this protein by Mdivi-1, studied both in vivo in apolipoprotein E (ApoE)-/- mice and in vitro in HUVECs, resulted in athero-protective effects, which suggests its potential as a therapeutic target for multiple CVDs, including atherosclerosis." (PMID 38392289, 2024). "Therefore, the aim of the present study was to explore the effect of MO on atherosclerosis and the potential mechanism by using ApoE−/− mice." (PMID 38410635, 2024). "ApoE−/− mice were fed HFD for 14 weeks to investigate the impact of SAMB on atherosclerosis." (PMID 38839811, 2024). "Although APOE isoform-dependent effects on hepatic steatosis have not been investigated in mouse models before, APOE deficient mice not only develop atherosclerosis but also NASH pathology including liver steatosis and fibrosis upon high-fat diet feeding." (PMID 37450924, 2024). "Therefore, we tested the PAC1 receptor agonist Maxadilan and the PAC1 selective antagonist M65 on plaque development and lumen stenosis in the ApoE−/− atherosclerosis model for possible effects on atherogenesis." (PMID 39769009, 2024). "Meanwhile, atherosclerosis-driven dysfunctional/plastic interferon- γ (IFNγ) +C-C motif chemokine receptor 5 (CCR5) + Th1-Tregs in ApoE−/− mice show reduced TIGIT expression, suggesting that TIGIT plays a stabilizing role in Tregs, helping to suppress inflammation." (PMID 39926714, 2024). "We studied the impact of E. faecium on the development of atherosclerotic lesions in ApoE−/− mice to determine if it could potentially mitigate the advancement of atherosclerosis." (PMID 39451408, 2024). "Moreover, aged garlic extract was found to inhibit inflammation in apolipoprotein E-knockout mice, a well-known model of hyperlipidemia and atherosclerosis." (PMID 39203947, 2024). "From these findings, it was concluded that E. faecium NCIMB11508 could potentially prevent the progression of atherosclerosis in ApoE−/− mice." (PMID 39451408, 2024). "In this study, we demonstrated that leflunomide treatment effectively decreased atherosclerotic plaque area both in the en-face aortas and aortic sinus and had a strong anti-atherosclerosis effect in WD-fed ApoE-/- mice through regulating lipid metabolism and vascular function." (PMID 39113703, 2024). "Elevated plasma TC levels are a main atherogenic factor for the formation of atherosclerosis; therefore, this mechanism may be particularly relevant in male apoE KO rabbits, as they exhibit “higher” hypercholesterolemia compared to WT rabbits." (PMID 39087075, 2024). "To investigate whether IF attenuates acrolein-induced development of atherosclerosis, we divided the ApoE−/− mice into four groups that were fed a high-fat diet." (PMID 38807423, 2024). "Moreover, while both male and female ApoE (−/−) mice spontaneously develop atherosclerosis, the females are generally found to have worsened atherosclerotic development than males even with similar serum lipid and chemistry levels." (PMID 38659910, 2024).
atherosclerosis (continued). "However, both models are very suitable to study inflammation in atherosclerosis development, while the APOE*3-Leiden.CETP model seems most suited to study the lipid-modulating effects of interventions on atherosclerosis development." (PMID 38428154, 2024). "APOE genotypes, especially APOE4, have similarly been associated with an increased risk of CVD phenotypes including CAD, atherosclerosis, dilated cardiomyopathy, CHD, hypercholesterolemia, ischemic heart disease, coronary sclerosis, stroke, and cardiovascular mortality, though not universally." (PMID 39766777, 2024). "We know, the arterial plaque formed by ApoE gene knockout (ApoE−/−) mice fed with high-fat diet is very similar to the pathological morphology and pathological process of human AS, which is a classic model of atherosclerosis." (PMID 38498570, 2024). "CD47−/−/ApoE−/− mice are protected from atherosclerosis, and systemic inhibition of SIRPα -mediated signaling appears more effective in reducing the necrotic core area in murine atherosclerosis models compared to global CD47 inhibition." (PMID 39926714, 2024). "Moreover, in atherosclerosis-prone apolipoprotein E (ApoE) KO mice, increased GSK3β serine phosphorylation (presumably including Ser9) was observed at atherosclerotic lesions." (PMID 39125833, 2024). "While some studies have identified an increase in miR-146a within human atherosclerotic plaques and a protective effect against atherosclerosis in hyperlipidemic mice via ApoE-mediated upregulation, others report a pro-atherogenic effect where miR-146a absence reduced atherosclerosis." (PMID 39403372, 2024). "Furthermore, a recent study has demonstrated that Tanshinone IIA effectively mitigates atherosclerosis by attenuating lipid accumulation and promoting autophagy in ApoE−/− mice fed with a high-fat diet." (PMID 38910885, 2024). "In atherosclerosis-prone ApoE−/− mice, S100A12 was shown to enhance calcification of the aorta." (PMID 39194749, 2024). "Therefore, the present study was conducted to investigate the protective effects and potential mechanisms of neoagarotetraose on high-fat, high-cholesterol diet (HFHCD)-induced atherosclerosis in ApoE−/− mice." (PMID 38794740, 2024). "Indeed, GSK126 has been recently shown to decrease the expression of inflammatory and proatherogenic genes in macrophages and atherosclerotic plaques, attenuating the development of atherosclerosis in ApoE−/− mice fed with high-fat diet." (PMID 38580969, 2024). "Hyperglycemia or exogenous glucosamine supplementation increases flux through the HBP and is associated with the induction of ER stress and unfolded protein response activation in vascular cells as well as the development of hepatic steatosis and accelerated atherosclerosis in apoE−/− mice." (PMID 38732122, 2024). "Also, in the context of atherosclerosis, it was shown that the increase in α2,3-sialylation in ApoE−/− mice potentially increases the size of atherosclerotic areas and the numbers of macrophages in the lesion, without affecting plasma cholesterol levels." (PMID 39616371, 2024). "Our study indicates that MerTK decrease in macrophages contributes to the aggravated atherosclerosis in diabetic ApoE–/– mice and regional restoration of MerTK in macrophages of the plaque via HMNVs could be a promising therapeutic approach." (PMID 38614985, 2024). "Regarding atherosclerosis, ApoE−/− IL-1Ra−/− mice showed more pronounced signs of arterial inflammation and destruction of the elastic laminae during plaque development compared to ApoE−/− mice." (PMID 39232217, 2024). "This might be one important reason why paeonol can inhibit the development of atherosclerosis in ApoE−/− mice." (PMID 38202844, 2024). "Intracranial atherosclerosis of apoE KO rabbits was reported in previous studies." (PMID 39087075, 2024). "The ApoE−/− line is also a very well‐studied model of atherosclerosis." (PMID 38979792, 2024).